PRKAR1A (protein kinase cAMP-dependent type I regulatory subunit alpha)
Diseases named in the same sentence as PRKAR1A in open-access papers (continued):
Sharing a sentence is not in itself a finding about the gene and the disease.
tumor (64 papers, 2006 to 2026). "These are rare and aggressive neoplasms that frequently have loss-of-function mutations in the PRKAR1A gene, which encodes a negative regulator subunit of PKA." (PMID 39804140, 2025). "Genomic profiling revealed EGFR and JUN amplifications with NCOR1 and PRKAR1A losses, alterations linked to aggressive tumor biology." (PMID 40979503, 2025). "Protein Kinase cAMP-Dependent Type I Regulatory Subunit Alpha (PRKAR1A) encodes a tumor suppressor that negatively regulates PKA activity, and AUTR Myh6-Cre driven loss of Prkar1a caused embryonic lethality." (PMID 39323506, 2024). "Pathogenic mutations of the PRKAR1A gene were identified in tumor specimens from four cases of sporadic cardiac myxoma, and the absence of these mutations in peripheral blood samples demonstrated that they were somatic mutations." (PMID 38310436, 2023). "Studies have demonstrated that the activation of PKA, facilitated by the removal of its regulatory subunit because of mutations in PRKAR1A tumor suppressor gene, which is responsible for CNC1, can induce FTC." (PMID 38074042, 2023). "CNC manifests as a result of inactivating mutations occurring within the tumor-suppressor gene known as PRKAR1A, which is responsible for encoding the regulatory subunit of protein kinase A (PKA) type 1α." (PMID 38074042, 2023). "The tumor C further progressed with stop loss mutation of PRKAR1A (c.1012T>G/p.Ter338Gluext*) with VAFs of ~0.18." (PMID 35853873, 2022). "CNC is caused by inactivating mutations in the tumor-suppressor gene encoding the cyclic AMP (cAMP)-dependent protein kinase A (PKA) type 1α regulatory subunit (PRKAR1A) mapped in chromosome 17 (17q22–24)." (PMID 34359735, 2021). "Correspondingly, deletion of 1 allele of Prkar1a dramatically accelerated OS formation in mice with Ocn-SV40 T antigen with tumours arising within 5 weeks of birth." (PMID 23036272, 2012). "Because general homozygous loss of Prkar1a is lethal in early mouse embryos, various haploinsufficiency and tissue-specific knock-out models have been engineered to demonstrate its tumour suppressor activity." (PMID 20548949, 2010). "A molecular genetic study demonstrated that more than 70% of CNC patients have mutations in the PRKAR1A gene, which is a classic tumor suppressor gene that encodes for the 1-α regulatory subunit (R1α) of the cyclic adenosine monophosphate (cAMP)-dependent protein kinase A (PKA)." (PMID 36092889, 2022). "In combination, these studies demonstrated that cAMP or PKA signaling or both play an important role in tumor development and that additional factors may contribute to Prkar1a haploinsufficiency in causing those tumors." (PMID 34359735, 2021). "In addition, allelic loss occurred in a portion of tumor cells, as indicated by genetic analysis, suggesting that complete loss of Prkar1a plays a vital role in tumor formation." (PMID 34359735, 2021). "Among the nine other main spleen proteins concerned with a complete reversion of the increase produced by tumor progression, we found two proteins involved in cell transduction pathways, one located in the cytosol (encoded by Prkar1a), and the second in the nucleus (encoded by Mapk3)." (PMID 34445271, 2021). "Since loss of PRKAR1A is sufficient to cause endocrine (as well as exocrine) tumorigenesis in the pancreas, PRKAR1A may play a key role in tumor-stroma crosstalk." (PMID 30519576, 2018). "Thus, complete loss of Prkar1a using heart-, Schwann cell- or pituitary-specific knockouts was required to induce tumours in these tissues." (PMID 20548949, 2010). "PRKAR1A is a key component of the cAMP signaling pathway that has been implicated in endocrine tumorigenesis and could, at least partly, function as a tumor suppressor gene." (PMID 16756677, 2006).
tumor (continued). "Data initially suggested that PRKAR1A functions as a “classic” tumor-suppressor gene, with loss of heterozygosity at the PRKAR1A locus in tumor tissue, however some data show that haploinsufficiency of PRKAR1A may be adequate for increased PKA activity and the early development of certain tumors." (PMID 33776926, 2021). "Integration of both NGS datasets showed that 14 of 24 cases (58%) displayed PRKAR1A gene variants with an average median VAF of 21%, due to the relative low tumor percentage." (PMID 39966109, 2025). "In 70% of cases, inactivating mutations are identified in the PKA regulatory 1-alpha subunit (PRKAR1A), a tumor suppressor gene." (PMID 37328870, 2023). "A number of potential collaborative tumor suppressor genes were identified in the in vivo screen, with Axin1 and Prkar1a selected for further investigation." (PMID 35000262, 2022). "For further analysis, we selected two candidate genes, Axin1 and Prkar1a, in addition to the canonical tumor suppressor Pten." (PMID 35000262, 2022). "PRKAR1A gene mutations cause R1α loss, augment PKA activity, and enhance downstream signaling, which lead to uncontrolled tumor suppression." (PMID 36092889, 2022). "The tumour-intrinsic factors inversely associated with the reported score such as EGFR, PRKAR1A and MAP3K1 are frequently associated with immune-suppressive phenotypes." (PMID 33139798, 2021). "For instance, in adrenal gland adenocarcinomas, chromothriptic events are predominantly detected on chromosomes 17, 19 and 22, affecting driver genes known to play an essential role in this tumour entity, such as PRKAR1A, MLL4, CCNE1 and ZNRF3, respectively." (PMID 32385320, 2020). "It has been demonstrated that CNC is caused by inactivating mutations in PRKAR1A gene, which is a regulatory subunit of PKA, suggesting that dysregulation of PKA signaling can cause tumor formation in the thyroid gland, and in other affected tissues." (PMID 31798532, 2019). "PRKAR1A is a tumor suppressor in the pancreas and points to the PKA pathway as a possible therapeutic target for these lesions." (PMID 30519576, 2018). "The pro-inflammatory phenotype of miR-1246 in MSCs was independent of TNFα stimulations and mediated by direct targeting of the tumor-suppressors PRKAR1A and PPP2CB." (PMID 28159925, 2017). "PRKAR1A has been described as tumor-suppressor in several cancer entities, and ablation of PRKAR1A has recently been shown to induce mammary neoplasia." (PMID 28159925, 2017). "The re-expression of PRKAR1A in H1299 cells suppressed the tumor cell proliferation and migration; stable knockdown (KD) of PRKAR1A in A549 cells enhanced this function both in vitro and in vivo." (PMID 27995993, 2016). "The clinical relevance of PRKAR1A has been significantly correlated with a tumor, lymph node, and metastasis stages (TNM)." (PMID 27995993, 2016). "The low levels of PRKAR1A transcript were correlated with tumor progression and poor overall survival." (PMID 27995993, 2016). "In order to elucidate the function of PRKAR1A in tumorigenesis in vivo, an experimental metastasis assay was utilized to compare the metastatic tumor nodules formed in the lungs of nude mice." (PMID 27995993, 2016). "The expression of PRKAR1A decreased with tumor progression, the size of tumors, lymph node metastasis, and also with the higher stages (III, IV) of adenocarcinomas." (PMID 27995993, 2016). "This provided an additional clarification for the correlation of PRKAR1A expression with tumor progression and metastasis." (PMID 27995993, 2016).
tumor (continued). "In Prkar1a+/− tumor cells, IF analysis demonstrated that β-catenin exhibited strong co-localization with PML in tumor cells." (PMID 25299576, 2014). "In most cases, CNC is caused by inactivating mutations in the gene encoding for the protein kinase A type 1A regulatory subunit (PRKAR1A), which is a tumor suppressor." (PMID 24499519, 2014). "The important role of the cAMP pathway in OS has been demonstrated in mice, in which a cAMP-dependent protein kinase (Prkar1a) has been shown to suppress OS tumor growth." (PMID 24984297, 2014). "Further analysis of tumours derived in this model revealed a recurrent genomic deletion of the Prkar1a gene." (PMID 23036272, 2012). "The analysis of human tumours found a subset of human OS also habour a Prkar1a deletion, demonstrating the power of mouse models to uncover new information into the complex genetics of human OS." (PMID 23036272, 2012). "Prkar1α was recently proposed as another tumor suppressor gene involved in osteosarcomagenesis in the mouse." (PMID 21403899, 2011). "The verification should be performed by a pathologist experienced in Carney complex, and staining for PRKAR1A protein may be helpful to distinguish between these two types of tumours." (PMID 39217593, 2024). "Therefore, will KIF1C exert its potential tumor-suppressing function via transcriptionally regulating PRKAR1A?" (PMID 37452081, 2023). "PRKAR1A haploinsufficiency is a general tumorigenic signal which may require inactivation of other tumour suppressors to function." (PMID 36760809, 2022). "Transcriptional profiling of such a large cohort of a single molecular type of cancer allows for a thorough understanding of the tumor’s genomic landscape, including the identification of genes affected by mutations (GNAS, MYCN, PPM1D, and PRKAR1A), and fusion transcripts (ZBTB20 and NCOR1)." (PMID 33741928, 2021). "Moreover, KD of PRKAR1A in A549 cells promoted the statistical colonization of circulating tumor cells to the lungs in nude mice." (PMID 27995993, 2016). "Antisense strategies against PRKAR1A have been used to suppress tumor malignancy in several cancer cell types and have been successfully applied in a combinational treatment in different tumor entities in vivo." (PMID 26203557, 2015). "Taken together, these studies clearly identified PRKAR1A as a tumor suppressor gene affecting several cell types in both humans and mice but left it unclear as to whether PKA defects might lead to a predisposition to hematologic malignancies." (PMID 26608815, 2015). "In the present study, we identified elevated levels of ADCY2 and PRKAR1A transcripts in a database of SI NETs compared to normal SI mucosa, suggesting that cAMP signaling may indeed be activated in tumor cells." (PMID 21853033, 2011). "Both approaches indicate that haploinsufficiency for Prkar1a predisposes to tumour formation in a spectrum of endocrine and non-endocrine tissues that are cAMP-responsive; the mouse phenotype partially overlaps with the human one." (PMID 20548949, 2010). "In the tumors of CNC patients loss of heterozygosity (LOH) at 17q22-24 may be observed, suggesting that PRKAR1A is a tumor suppressor gene." (PMID 16756677, 2006). "Germline mutation of PRKAR1A was negative, although a pathogenic PRKAR1A mutation was identified on tumor sequencing and mosaicism for germline PRKAR1A mutation could not be excluded." (PMID 37966258, 2023).
tumor (continued). "Germline mutations occur in several known genes (AIP, PRKAR1A, GPR101, GNAS, MEN1, CDKN1B, SDHx, MAX) as well as familial cases with currently unknown genes, while somatic mutations in GNAS are present in up to 40% of tumours." (PMID 33805450, 2021). "However, some individuals with CCx present with a sporadic type of inheritance or do not show an identifiable mutation of the PRKAR1A gene (a tumor suppressor gene)." (PMID 32011473, 2020). "Mutations in PRKAR1A were previously not thought to be responsible for the development of isolated, sporadic cardiac myxomas, but genetic alterations in this gene have recently been identified in a minority of such tumor samples." (PMID 31874650, 2019). "Moreover, we examined whether PRKAR1A alteration could contribute to tumor formation and growth in vivo, especially in the lung." (PMID 27995993, 2016). "Top neoantigen targets for SHH included DDX3X, PRKAR1A, and PTCH1 which are genes commonly involved in tumor progression." (PMID 39160595, 2024). "To validate the regulation of PRKAR1A and PRKACB by miR-200c, we correlated mRNA expression of both PKA subunits to miR-200c expression in the NCI-60 panel of tumor cell lines." (PMID 26203557, 2015). "Tumour-specific loss of heterozygosity within the chromosomal region harboring PRKAR1A is observed in tumours from CNC patients and isolated PPNAD, suggesting that PRKAR1A is a potential tumour suppressor gene." (PMID 20548949, 2010).
cancer (33 papers, 2012 to 2025). A tumor composed of atypical neoplastic, often pleomorphic cells that invade other tissues. "Patient M1 had three variants in cancer-related genes (PRKAR1A c.221G>A; COL7A1 c.7313C>G; and MTAP c.634T>C)." (PMID 32443704, 2020). "In conclusion, this study proposes PRKAR1A as a promising diagnostic and therapeutic marker for cancer, highlighting its functional role as a biomarker which could contribute to the development of novel strategies in anticancer treatments." (PMID 38474121, 2024). "Therefore, examination the ERK pathway and its association with EMT provides a crucial link between PRKAR1A, cancer malignancy, and stemness." (PMID 38474121, 2024). "In summary, these results suggest that the downregulation of PRKAR1A expression increases resistance to anticancer agents, leading to enhanced cancer cell-killing effects." (PMID 38474121, 2024). "Our findings demonstrated that PRKAR1A exerts its effects on cells with different patterns in both cancer and cancer stem cells." (PMID 38474121, 2024). "This study elucidates how PRKAR1A affects EMT in cancer cells and MET in CSCs through ERK phosphorylation, establishing its role in cell behavior." (PMID 38474121, 2024). "When PRKAR1A was overexpressed in all cancer types, the survival period would begin to significantly decrease compared to than in patients with a low expression of this protein at a specific time point." (PMID 38474121, 2024). "The identified biomarker, PRKAR1A, exhibited expression in both cancer cells and CSCs, showcasing its ability to regulate EMT and stemness through the ERK signaling pathway." (PMID 38474121, 2024). "In the cell proliferation assay, the downregulation of PRKAR1A expression increased the proliferation of all the cancer cells tested but decreased proliferation in CSCs in a time-dependent manner." (PMID 38474121, 2024). "Given the differential effect of PRKAR1A on the migration of various cell types, we examined its role in cancer cells and CSCs using a scratch assay." (PMID 38474121, 2024). "The downregulation of PRKAR1A expression increased cyclin D1 expression and the S phase length of the cancer cells." (PMID 38474121, 2024). "Taken together, the implications of these results are quite significant and the clinical application of PRKAR1A is quite limited because this protein functions oppositely in cancer cells and CSCs." (PMID 38474121, 2024). "The clinical outcomes associated with elevated levels of PKRAR1A underscore its significance as an unfavorable prognostic factor in cancer, emphasizing the critical need for further research on PRKAR1A in the context of cancer." (PMID 38474121, 2024). "We assessed the effects of PRKAR1A knockdown on the biological functions of cancer cells and CSCs using shRNA." (PMID 38474121, 2024). "In summary, our findings demonstrate that the downregulation of PRKAR1A expression increases cell proliferation in cancer cells but decreases it in CSCs." (PMID 38474121, 2024). "We examined the ERK phosphorylation-mediated regulatory role of PRKAR1A shRNA in the EMT of cancer cells." (PMID 38474121, 2024). "To assess the biological functions of PRKAR1A in cancer cells and CSCs, we generated a series of short hairpin RNAs (shRNA) to downregulate PRKAR1A expression in each cell line." (PMID 38474121, 2024). "The evaluation of PRKAR1A expression in patients with cancer using TCGA data revealed low expression of this protein in certain cancer types." (PMID 38474121, 2024). "The confirmation of the downregulation of the drug-resistance gene MDR1 demonstrated that PRKAR1A induced chemoresistance in both the cancer cells and the CSCs through the regulation of MDR1 expression." (PMID 38474121, 2024). "Here, we define the tissue distribution of genetic alterations in PRKACA and PRKAR1A that result in PKA activation in cancer and map the multiple conserved pathways downstream of oncogenic PKA signaling, many of which impinge on the expression of c-MYC." (PMID 36692000, 2023).